MIR6889 (microRNA 6889)
Synonyms: hsa-mir-6889
Gene: MicroRNA gene on chromosome 22 (41,252,992 to 41,253,050, reverse strand). Ensembl gene ENSG00000274552.
Homologues: Orthologues: chimpanzee MIR6889 (100% identical).